ZNF804A (zinc finger protein 804A)
Diseases named in the same sentence as ZNF804A in open-access papers (continued):
Sharing a sentence is not in itself a finding about the gene and the disease.
autism (2 papers, 2016 to 2019). Persistent deficits in social interaction and communication and interaction as well as a markedly restricted repertoire of activity and interest as well as repetitive patterns of behavior. "This family-based association study was performed in 640 Han Chinese autism trios to investigate the relationships between two SNPs (rs1344706 and rs7603001) in ZNF804A and autism." (PMID 31122238, 2019). "Only one study explored the significance of ZNF804A polymorphisms in autism, which discovered that rs7603001 was nominally associated with autism." (PMID 31122238, 2019). "In addition, rs7603001 in ZNF804A was nominally associated with autism (P = 0.018) in 841 autistic families from the Autism Genetic Resource Exchange (AGRE), most of whom were white." (PMID 31122238, 2019). "Therefore, the association between autism and other SNPs, and/or structural abnormalities in ZNF804A should be further investigated." (PMID 31122238, 2019). "Here, we investigated whether these two SNPs (rs1344706 and rs7603001) in ZNF804A contribute to the risk of autism in a Han Chinese population." (PMID 31122238, 2019). "Association studies in other populations are required to assess the involvement of ZNF804A in autism." (PMID 31122238, 2019). "Further research is needed to comprehensively explore the relationships between ZNF804A and autism." (PMID 31122238, 2019). "Second, other SNPs or structural abnormalities such as copy number variations (CNVs) in ZNF804A might be involved in the etiology of autism." (PMID 31122238, 2019). "Moreover, no previous study investigated the association between ZNF804A and autism in a Han Chinese population." (PMID 31122238, 2019). "Our findings suggested that rs1344706 and rs7603001 in ZNF804A might not be associated with autism in a Han Chinese population." (PMID 31122238, 2019).
Autoimmunity (2 papers, 2015 to 2017). The occurrence of an immune reaction against the organism's own cells or tissues. "Of them 12 are associated with other autoimmune diseases than SLE, whereas three genes (ZNF804A, CDK1, and MANF) have not previously been associated with autoimmunity." (PMID 28740209, 2017). "The findings suggest that ZNF804A may affect a differentiating neuron’s response to inflammatory cytokines, which is consistent with models of SZ and ASD that support a role for infectious disease, and/or autoimmunity in a subgroup of patients." (PMID 25905630, 2015).
depression (2 papers, 2020). "Three replicated loci were previously reported (ITIH3, FHIT, BAG5), but the other seven (ZNF804A, MIR3143, PSORS1C2, STK19, SPATA31D1, RTN1, TCF4) were novel for depression." (PMID 30626913, 2020).
Gingival bleeding (2 papers, 2019 to 2022). Hemorrhage affecting the gingiva. "It is important to highlight that the identification of genes with hypomethylated states in individuals with gingival bleeding would correspond to an increase in the upregulation of gene expression, so ZNF804A should be considered as a gene related to gingival tissue inflammation." (PMID 36233348, 2022).
neuroblastoma (2 papers, 2019). Neuroblastoma (NB) is the most common solid, extracranial childhood tumor. "To further investigate the role of ZNF804A in gene regulation (expression and splicing), we used exon arrays to determine the effect of acute ZNF804A depletion on the transcriptome of SH-SY5Y neuroblastoma cells." (PMID 30597088, 2019). "The co-transfection results in human neuroblastoma SK-N-AS cells showed that the overexpressed HSF2 decreased the ZNF804A transcription level, and its inhibition effect on the T allele was stronger than on the C allele." (PMID 30670685, 2019). "To test the hypothesis that ZNF804A may be involved the regulation of gene expression and pre-mRNA processing, we used siRNAs to knockdown endogenous ZNF804A in the SH-SY5Y neuroblastoma cell line." (PMID 30597088, 2019).
Alcohol (1 paper, 2021). "Alcohol problem severity shows a main effect on impulsivity, and the SNP ZNF804a rs1344706 and education year showed moderating effects." (PMID 35046850, 2021). "First, alcohol problem severity during alcohol withdrawal in men hospitalized for alcohol dependence showed a main effect on impulsivity, and the SNP ZNF804a rs1344706 showed a moderating effect." (PMID 35046850, 2021). "Based on the framework of G×E research on the etiology of AUD-related psycopsychiatrical issues, this study examined the interaction between ZNF804a rs1344706 and alcohol problem severity during withdrawal on impulsivity in Han Chinese patients diagnosed with alcohol dependence." (PMID 35046850, 2021).
autoimmune disease (1 paper, 2017). A disorder resulting from loss of function or tissue destruction of an organ or multiple organs, arising from humoral or cellular immune responses of the individual to their own tissue constituents. "The random forest classification predicted ZNF804A, ANK3 and DOCK3 that have so far not been connected to SLE or any other autoimmune disease to be risk genes for SLE." (PMID 28740209, 2017).
bleeding (1 paper, 2019). "To further explore the functional relevance of the most associated gingival bleeding DNA methylation signal in ZNF804A, we correlated the methylation levels at the most associated CpG site in this gene (cg21245277) with 271 known fasting blood metabolites profiled by mass spectrometry." (PMID 30760334, 2019).
Dyskinesia (1 paper, 2015). A movement disorder which consists of effects including diminished voluntary movements and the presence of involuntary movements. "For genes that decreased in the ZNF804A KDs, the top disease pathways and biological functions were neuromuscular disease, dyskinesia, movement disorders and Huntington's Disease." (PMID 25905630, 2015).
mental disorder (1 paper, 2021). A disease that has its basis in the disruption of mental process. "GWAS studies showed that SNP variants within ZNF804A are associated with mental disorders, especially SZ." (PMID 33303946, 2021).
mental retardation (1 paper, 2012). "This score together with the described involvement of zinc finger genes in mental retardation make ZNF804A a candidate gene for cognitive and behavioral disturbances, consistently with previous findings involving other zinc-finger genes in mental retardation." (PMID 22550961, 2012).
pancreatic cancer (1 paper, 2021). "The key findings of the current study highlights ZNF804A, ZFP82, TRIM58, SOX17, and C12orf42 as hypermethylated/downregulated genes in pancreatic cancer associated with the development and progression of pancreatic cancer through their modulation of specific pathways." (PMID 33833773, 2021). "In the current study, 5 hypermethylated/downregulated genes in pancreatic cancer were identified, including ZNF804A, ZFP82, TRIM58, SOX17, and C12orf42, all of which were found to be correlated with the poor survival of pancreatic cancer patients." (PMID 33833773, 2021). "Univariate Cox model and Kaplan–Meier method revealed that, among 31 MeDEGs, 5 hypermethylated/downregulated genes (ZNF804A, ZFP82, TRIM58, SOX17, and C12orf42) were correlated with poor survival of patients with pancreatic cancer." (PMID 33833773, 2021). "Taken together, the key findings of the current study demonstrate that ZNF804A, ZFP82, TRIM58, SOX17, and C12orf42 are hypermethylated/downregulated genes in pancreatic cancer and may be associated, through their modulation of specific pathways, with unfavorable pancreatic cancer prognosis." (PMID 33833773, 2021).
Syncope (1 paper, 2021). A transient loss of consciousness (i.e., characterized by a rapid onset, a short duration, and a spontaneous and complete recovery) due to cerebral hypoperfusion. "Functional annotation identified 26 genes in the locus associated with a risk of syncope; the researchers believe that the ZNF804A gene encoding zinc finger protein 804A is the most plausible candidate gene associated with the risk of developing VVS." (PMID 34638656, 2021).
viral infection (1 paper, 2015). "Overall, our results suggest that ZNF804A modulates the expression of genes that regulate cytokine and chemokine signaling pathways in differentiating neurons, perhaps affecting their response to immune activation and/or viral infection." (PMID 25905630, 2015).
psychiatric disorder (9 papers, 2013 to 2024). A disorder characterized by behavioral and/or psychological abnormalities, often accompanied by physical symptoms. "Our findings provide new insights into the role of ZNF804A polymorphisms in the pathogenesis of psychiatric disorders." (PMID 30670685, 2019). "GWAS identified strong evidence for association of the zinc finger protein 804A (ZNF804A) gene (located on the long arm of chromosome 2 at the 2q32.1) with psychiatric disorders including both BD and SZ." (PMID 23351715, 2013). "Besides single nucleotide polymorphisms (SNPs), CNVs of ZNF804A have been reported in patients with psychiatric diseases." (PMID 33446247, 2021). "It reveals new roles of ZNF804A polymorphisms in the pathogenesis of psychiatric disorders." (PMID 30670685, 2019). "However, the risk allele of rs1344706 associated with other major mental illnesses has been shown to be associated with higher ZNF804A expression." (PMID 23351715, 2013). "Collectively, our results demonstrate that ZNF804A plays a critical role in the neuronal development and interacts with multiple factors to modulate to these cellular processes, which are relevant to the progression of psychiatric diseases." (PMID 33446247, 2021). "Therefore, to fully understand how this protein may contribute to the pathophysiology of psychiatric disorders it is critical to fully understand the distribution of all isoforms of ZNF804A and, furthermore, the functional roles they play." (PMID 27837918, 2017). "Studies of its biological functions in vitro have indicated that ZNF804A is involved in cell adhesion, neurite growth, synaptic transmission, and RNA translation, any or all of which may affect brain functions and contribute to the development of psychiatric disorders." (PMID 33303946, 2021). "Further research is needed to elucidate the role of ZNF804A and TCF7L2 in thalamus development and in the etiology of psychiatric disorders." (PMID 25963709, 2016). "However, no in vivo data are available for the role of ZNF804A in psychiatric disorders in general, SZ in particular." (PMID 33303946, 2021).
neurodevelopmental disorder (4 papers, 2017 to 2023). A behavioral and cognitive disorder with onset during the developmental period that involves impaired or aberrant development of intellectual, motor, or social functions. "Finally, we used gene set enrichment analysis to search for associations between DEX and differentially spliced genes in ZNF804A-depleted cells and genes implicated in several common neurodevelopmental disorders." (PMID 30597088, 2019). "In another study, an excess of CNVs in ZNF804A was detected in 19,556 patients with neurodevelopmental disorders compared with 13,991 controls (P = 0.047)." (PMID 31122238, 2019). "Importantly, because risk variants in ZNF804A appear to alter its developmental expression, our data provide an insight into how this could contribute to the pathophysiology of psychotic and neurodevelopmental disorders." (PMID 27837918, 2017).
tumor (2 papers, 2020 to 2021). "Among which, the hypermethylation of ZNF804A, ZFP82, TRIM58, SOX17, and C12orf42 were all noted to be significantly associated with tumor-related pathways, including calcium signaling pathways, neuroactive ligand-receptor interaction, glycosynthetic ganglion series and intercellular junctions." (PMID 33833773, 2021).
infectious disease (1 paper, 2015). A disorder directly resulting from the presence and activity of a microbial, viral, or parasitic agent in humans. "This suggests that reduced expression caused by a decrease in ZNF804A could make differentiating neurons more vulnerable to infectious disease, autoimmune attack or cellular stress." (PMID 25905630, 2015).
nervous system disorder (1 paper, 2021). A non-neoplastic or neoplastic disorder that affects the brain, spinal cord, or peripheral nerves. "Future detailed studies and analysis on this mouse model may help to gain a better understanding of the role of ZNF804A in the adult brain and in nervous system disorders." (PMID 33303946, 2021).
ZNF804A also shares sentences with these, for which no sentence is quoted: chronic periodontitis (2 papers); allergic rhinitis (1); anxiety disorder (1); asthma (1); attention deficit-hyperactivity disorder (1); breast carcinoma (1); cancer (1); celiac disease (1); dementia (1); epilepsy (1); Huntington disease (1); lung adenocarcinoma (1); malaria (1); metabolic syndrome (1); movement disorder (1); neuromuscular disease (1); periodontal disease (1); schizoaffective disorder (1).